TNF (tumor necrosis factor)
Diseases named in the same sentence as TNF in open-access papers (continued):
Sharing a sentence is not in itself a finding about the gene and the disease.
bacterial infection (continued). "The possible role of NK cells on UTIs (or bacterial infections) via tumor necrosis factor (TNF) production was reported." (PMID 33919913, 2021). "Production is, however, activated in all parenchymal organs in response to bacterial infection, mediated by cytokines: interleukin-6 (IL-6), tumor necrosis factor-α (TNF-α) and interleukin-1β (IL-β)." (PMID 34577795, 2021). "It was previously shown that in vitro knockdown of NLRP12 up-regulated IL-6 and TNF-α expression in bacterial infections, such as salmonella and Klebsiella pneumonia infection." (PMID 34956178, 2021). "Pre-treatment of Zetnf-b polyclonal antibody and TNF inhibitor AG126 can help zebrafish to resist bacterial infections and improve the survival of zebrafish." (PMID 34869718, 2021). "NGAL acts as mediator of the innate immune response to bacterial infections, and its expression is induced by TNFα and IL-6." (PMID 34944574, 2021). "TNF-α is a potent mediator found abundantly in granules of mast cells and is released by degranulation upon bacterial infection for clearing pathogens." (PMID 33802578, 2021). "These M1-like MΦs help control bacterial infection; however, excessive TNFα in the microenvironment can result in sustained Mincle expression and MΦ inflammatory responses." (PMID 34320039, 2021). "Due to its well-characterized effects on MΦ including the induction of the potent pro-inflammatory cytokine TNF-α, this intensively studied compound is best suited to examine the effects of bacterial infections on MΦ." (PMID 34975859, 2021). "As expected, bacterial infection induced a systemic inflammatory response characterized by increased plasmatic levels of TNFα, IL-6, IL-12, IFNγ and KC/GRO (CXCL-1) compared to PBS-treated mice." (PMID 34437647, 2021). "Neutrophils from systemic Cnlp−/− mice showed an increased level of TNF‐α after bacterial infection, but with decreased antimicrobial activity compared with wild‐type (WT) cells, indicating that CRAMP is important for normal neutrophil response to bacteria." (PMID 33104252, 2021). "Our results thus suggest further molecular mechanisms for crosstalk or cross-priming function of TNF to other immune pathways during viral and bacterial infections." (PMID 33431886, 2021). "TNF-α is critical for an effective antibacterial host defense against bacterial infection by regulating downstream cytokine response and activating immune cells." (PMID 34544549, 2021). "At the cellular level, the activation of macrophages, neutrophil granulocytes amongst other immune cells by LPS during bacterial infection or by cytokines (IL-1, TNF-α, or IFN-γ) induces overexpression of iNOS and overproduction of NO." (PMID 33924632, 2021). "Our data suggest that EBST enables host to rapidly produce Th1 derived cytokines—IFNγ and TNFα, in response to the virulent bacterial infection." (PMID 33861743, 2021). "TNF-α performs many functions, including preventing bacterial infections, regulating cell growth and the immune system, and participating in septic shock." (PMID 34992717, 2021). "BC contains many cytokines of relevance for immune modulation and cellular responses to stressors such as bacterial infection; these cytokines include TNFα, GMCSF, and interleukin (IL)-1β, -6, and -10." (PMID 33809940, 2021). "Under stimulation with LPS and/or IFN-γ, macrophages polarize into M1 macrophages to show pro-inflammatory phenotype and resist bacterial infection through the production of interleukin (IL)-1β, tumor necrosis factor (TNF)-α, and nitric oxidate (NO)." (PMID 32973770, 2020). "Immune cells especially, such as macrophages, are known to release large amounts of TNF-α during bacterial infections." (PMID 32316261, 2020). "This modulation of immunity is also supported by decreased levels of cytokines responsible for controlling bacterial infections, such as IL-1β, IL-6, IL-9, IL-12, TNF-α, IL-17, and IFN-γ, observed in the serum of the WT mice." (PMID 32139610, 2020).
bacterial infection (continued). "Here we show that macrophage DRP1 is a positive regulator of TNF-α production during sterile inflammation or bacterial infection." (PMID 33520735, 2020). "This prolonged IFN-I and virally induced IL-10 set the scene for secondary bacterial infection, which can add a strong IL1β and TNFα-mediated inflammatory response to magnify lung damage." (PMID 32595654, 2020). "SOCS family proteins were considered as the important regulators of inflammatory responses (like interferons and cytokines; IL6, TNFα) and being significantly induced by broad range of bacterial infections." (PMID 33585275, 2020). "Triggering the apoptotic pathway, induction of autophagy, stimulation of IFNγ and tumor necrosis factor alpha (TNFα) secretion are some of the mechanisms adopted by the host cells during bacterial infection." (PMID 32987746, 2020). "The Th1 pro-inflammatory cytokines IFN-γ and TNF-α are both involved in the defense against bacterial infections and in acute phase reactions." (PMID 32102262, 2020). "The body temperature and plasma inflammatory cytokines (TNF-α, IL-6) levels increased after bacterial infection at 24 h in all groups." (PMID 32221396, 2020). "Cytokines such as TNF-α, KC, IL-1β, and IL-10, released, among others, by PMNs, orchestrate the innate immune response in bacterial infections." (PMID 33613460, 2020). "The interaction of epithelial, endothelial and immune cells within the human alveolus-on-a-chip model demonstrates high amounts of TNF-α in response to bacterial infection." (PMID 32316261, 2020). "Direct downstream targets of endotoxins and bacterial infection include proinflammatory cytokines, such as interleukins and TNFα, which can subdue SCD1 expression." (PMID 32258419, 2020). "PM2.5-treatment plus bacterial infection inhibited the production of proinflammatory cytokines including IL-1α, IL-1β, and TNF-α, thereby enhancing bacterial infectivity." (PMID 32753046, 2020). "The potency of the tested flavonolignans to modulate the immune response was determined on LPS-induced macrophages by monitoring cytokine (TNF-α and IL-6) release as the first reaction, by which a healthy cell responds to the bacterial infection." (PMID 32466263, 2020). "Neutrophils, recruited by TNF-α and mast cell protease 6, are essential for fighting bacterial infections, while IL-8 can recruit natural killer cells to fight viruses." (PMID 33352850, 2020). "The defense process against a bacterial infection is initially mediated by pro-inflammatory cytokines, such as tumor necrosis factor alpha (TNF-α), interleukin (IL)-1, IL-6, IL-8, and IL-12, in addition to monocyte/lymphocyte infiltration." (PMID 33291232, 2020). "Apart from any bacterial infection, TNF-α is known to induce the release of large amount of PCT in both animals and humans." (PMID 32430795, 2020). "M1 polarization occurs via stimulation with several pro-inflammatory signals (e.g., LPS and IFNγ, with ensuing TNFα, and IL-6 production), as are normally elicited early after bacterial infection of the urinary tract." (PMID 32849562, 2020). "Bacterial infection first activates the host’s innate immune response, producing a series of inflammatory cytokines, such as TNF-α, IL-6, and IL-10." (PMID 32913259, 2020). "During viral and/or bacterial infection, the cytokine profile, including the expression of TNF-α, of infected cells is altered depending on the host cell type and on the pathogens." (PMID 32316261, 2020). "Tumor-necrosis factor-alpha (TNFα), important in the defense against bacterial infections, and in acute phase reactions is upregulated 6.10 ± 1.4 fold." (PMID 32045425, 2020). "Yet, the mRNA expression of SP-A is strongly down-regulated by TNF-α, which is highly produced by professional phagocytes in response to bacterial infection." (PMID 32316261, 2020). "In particular, TNF-α regulates inflammation and host defense in response to bacterial infection and is suppressed by acute stress." (PMID 30723745, 2019).
bacterial infection (continued). "The immune response will be amplified by proinflammatory cytokine secretion, including TNF-α, IL-1, and IL-6, which help to enhance the tissue permeability and recruit more phagocytes to clear the bacterial infection." (PMID 30728747, 2019). "For the studied Th1 cytokines (IFNγ, TNFα, IL-6, and IL-1β), only IFNγ showed a significant decrease as a consequence of bacterial infection in mechanically ventilated rats." (PMID 31614857, 2019). "Once hip fracture occurs, the trauma leads to intracellular mitochondrial fragmentation and induces the release of some proinflammatory factors similar to bacterial infection, such as tumor necrosis factor (TNF)-α, interleukin (IL)-6, and IL-1." (PMID 31410362, 2019). "Bacterial infection significantly induced the generation of IL-1β, IL-6, and TNF-α in BMMs treated with vehicle." (PMID 30609675, 2019). "For example, systemic inflammation induced by bacterial infection and stress activate microglia which then release cytokines tumor necrosis factor-α and IL-1β15,58." (PMID 31862977, 2019). "TNF-α, a principle mediator in host response to bacterial infection, is involved in the pathogenesis of Helicobacter spp." (PMID 31194753, 2019). "The production of IL-1β, IL-1α, TNF-α, and IL-6 was completely dependent on bacterial infection, but low levels of MCP-1 and MIP-1α were already detected in the supernatants from uninfected cultures." (PMID 30455194, 2019). "Use of pathway inhibitors resulted in a decrease in both IL-8 and TNF-α secretion by A549 cells following bacterial infection either alone, or following bacterial exposure to ECVE or CSE." (PMID 31847850, 2019). "It is generally acknowledged that necrosis is triggered by ROS production, ATP depletion and TNF-α synthesis that are induced upon bacterial infection." (PMID 31783504, 2019). "HIF-1α also functions as an important regulator for myeloid cells against bacterial infection by producing antimicrobial peptides, TNF-α, and nitric oxide." (PMID 31885781, 2019). "Among the producers of TNF-α during bacterial infection are Ly6C+ monocytes which will subsequently differentiate into M1 macrophages." (PMID 31114572, 2019). "In particular, TNF-α is produced by T and B cells, NK cells, and macrophages, and regulates inflammation and the host defense through inhibiting bacterial infections and suppressing acute stress." (PMID 31752816, 2019). "TNF-α is produced immediately upon pathogen-invasion, including bacterial infections, and induces various immune responses such as cell proliferation and inflammation." (PMID 30819151, 2019). "In a sublethal P. aeruginosa pulmonary infection, PvdQ treatment resulted in less lung inflammation as well as decrease of CXCL2 and TNF-α levels at 24 h post-bacterial-infection by 15 and 20%, respectively." (PMID 29755959, 2018). "It is also notable that expression of TNF-α mRNAs was also drastically suppressed in all the KO MEFs upon bacterial infection, suggesting a significant role of RIG-I/MAVS and STING signaling pathways in non-phagocytic host cells." (PMID 30233599, 2018). "PCT secretion is stimulated in bacterial infections by various cytokines, such as IL–1, IL–6, and tumor necrosis factor-alpha." (PMID 29891780, 2018). "SMER3 pretreatment of R848-primed BMDMs significantly decreased IL-1β and TNF-α production in response to bacterial infection." (PMID 29515583, 2018). "Weaning stress potentiated the neuroendocrine response to lipopolysaccharide (LPS) injection as a model for a bacterial infection and induced higher intensity sickness behavior, whereas plasma tumor necrosis factor (TNF) concentrations remained unaltered." (PMID 29666573, 2018). "It is worth noting that PRRSV infections are usually accompanied by secondary bacterial infection and abundant TNF-α in the lung, a significant part of the respiratory syndrome." (PMID 30469357, 2018).
bacterial infection (continued). "Previous reports showed that ILC1s induce IFN-γ- and TNF-α-mediated protection against parasitic as well as bacterial infections." (PMID 29623077, 2018). "Another study has shown that EVs derived from macrophages stimulated with bacterial infection are able to increase secretion of proinflammatory cytokines in recipient cells, including TNF." (PMID 29807527, 2018). "Others also showed that CREB phosphorylation can induce TNF-α production during bacterial infections." (PMID 30222739, 2018). "In this stage of bacterial infection, pro-inflammatory cytokines such as TNF-α, IL-1β, and IL-6 are elevated, playing a crucial role in the pathogenesis of acute bacterial infection." (PMID 30319993, 2018). "Previous studies have shown that melatonin suppresses TNF-α, IL-1β, IL-6, IL-8, and IL-10 during bacterial infections or LPS treatment in vitro and in vivo." (PMID 28542575, 2017). "ε-N-myristoylated are interleukin 1α (IL-1α) and tumor necrosis factor α (TNFα), the pro-inflammatory cytokines crucial in combating bacterial infections." (PMID 29403483, 2017). "During bacterial infection, IL-10 down-regulates Th1 by suppressing overexpressed immunopathology associated factors, such as IFN-γ and TNF-α, and subsequently preventing multiple severe immune responses." (PMID 29340060, 2017). "Treatment with atorvastatin prior to the bacterial infection had anti-inflammatory effects per se in the infected lung of both SB and MV animals according to TNF-α concentrations, as reported in vitro." (PMID 29149185, 2017). "In contrast to the case during bacterial infection, similar TNFα and IL-6 levels were observed between the virus-infected WT and SCD animals." (PMID 28256526, 2017). "On the other hand, the death of infected cells was demonstrated to play importantly in the outcome of bacterial infection and TNF is known as a potent stimulator of cell death such as apoptosis and necrosis." (PMID 29062811, 2017). "TNF mediates most pro-inflamatory effects that occur upon bacterial infection by promoting NFkB and MAPK activation." (PMID 28587645, 2017). "Pro-inflammatory cytokines such as TNF-α, IL-6 and IL-1β are essential for the recruitment and activation of cells of the immune system in response to bacterial infection." (PMID 28440335, 2017). "High levels of interleukin-10 prevent the release of pro-inflammatory cytokines tumor necrosis factor α and interleukin-1β which allow the bacterial infection in the mammary glands to remain dormant." (PMID 28542500, 2017). "M. tuberculosis up-regulates the production of tumor necrosis factor (TNF), an immune system component that controls bacterial infections, which activates HIV replication in macrophages." (PMID 28335562, 2017). "Bacterial infections seem to occur early, within the first 6 months after the initiation of TNF-α inhibitor therapies." (PMID 28179019, 2017). "It is induced in response to viral or bacterial infections and pro-inflammatory cytokines, such as IL-1, tumor necrosis factor (TNF)-α, or platelet derived growth factor (PDGF)." (PMID 29182557, 2017). "Because TNF-α and IL-6 are both important cytokines contributing to the host immune system against bacterial infection, we examined these cytokines in the bladder tissues of the experimental mice using the ELISA method." (PMID 26233310, 2016). "Paracrine TNFα signaling is an important aspect of bacterial infections as it recruits active immune cells capable of secreting TNFα within the milieu, resulting in diverse effects on resident cells." (PMID 27698456, 2016). "It is released by parenchymal cells, including liver cells, kidney cells, adipocytes, and muscle cells in response to endotoxin or mediators released during bacterial infections (e.g. interleukin (IL)-1b, tumor necrosis factor (TNF)-a, and IL-6)." (PMID 28856207, 2016). "After 6 h of bacterial infection, zebrafish muscles show high induction (∼200-fold) of pro-inflammatory cytokines IL1β and TNFα." (PMID 27101844, 2016).
bacterial infection (continued). "The upregulated genes included genes encoding innate immunity effectors, such as IL-17C, CCL20, and TNF, which contribute to combat bacterial infections." (PMID 26485688, 2015). "We then profile the response to subsequent bacterial infection and observe massive increases in both neutrophils and TNF-α." (PMID 26265006, 2015). "By our study, we also demonstrated that EPs 7630 preincubation of immune cells influenced their subsequent, by viral or bacterial infection-mimicking agents induced cytokine production towards an IL-6-dominated milieu, with lower TNF-α and IL-10 content." (PMID 26406906, 2015). "Apart from IFN-γ, IL-4 and IL-10, there are several cytokines, such as IL-12, IL-2, IL-1, IL-18 and TNF-α that are involved in the regulation of immune responses to bacterial infections." (PMID 26619346, 2015). "The role of pro-inflammatory molecules such as TNF-α in bacterial infection is complex contributing to host defence, but also participating in organ damage and lethality." (PMID 26338794, 2015). "These mice also exhibit differences in the amount of IL-10 and tumor necrosis factor (TNF) produced in response to bacterial infection." (PMID 26510153, 2015). "In response to viral or bacterial infections, the cells secrete pro-inflammatory cytokines, e.g. tumor necrosis factor-α (TNF-α) and interleukin-1β (IL-1β)." (PMID 24676726, 2015). "It has been known that IL-6 and TNF-α secretion by macrophages upon bacterial infection in turn enhances their phagocytic capacity, thus promoting the clearance of pathogens." (PMID 26439699, 2015). "The APR is the first response to various stressors, such as injury, bacterial infection or systemic inflammation, and is activated by inflammatory mediators, such as tumor necrosis factor alpha (TNFα), IL-1β, IL-6, and GCs." (PMID 25335188, 2014). "Thirdly, TNF α inhibitors increase the likelihood for bacterial infections, which activate polyclonal B-lymphocytes and result in antibody production." (PMID 24949211, 2014). "As a potent proinflammatory cytokine, TNF-α is released both by macrophages and T lymphocytes in response to bacterial infection." (PMID 24587010, 2014). "In the patients with bacterial infections, IL-1Ra and IL-8 demonstrated positive correlation with C-reactive protein, whereas, IL-1Ra, TNF-α, and MCP-1 correlated with procalcitonin." (PMID 23690657, 2013). "We determined the deglycosylation of SIRPα after bacterial infection, after TNFα stimulation, and under control conditions." (PMID 23448224, 2013). "The ability to induce pro-inflammatory cytokines such as TNF-α, along with the ability to multiply rapidly in macrophages during intracellular bacterial infection, is an important indicator of virulence." (PMID 23555735, 2013). "Upon exposure to bacterial infection, proinflammatory cytokines like TNFα, IL-1β, and IL-6 are secreted mostly by monocytes or macrophages to defend against bacterial infections." (PMID 23997804, 2013). "Since IL-12 or TNF-α have been shown to reduce bacilli burdens during bacterial infection, We evaluated if statin treatment also enhanced IL-12p40 and TNF- α production in BMDMs." (PMID 24086542, 2013). "The serum IL-1Ra levels of the patients with bacterial infections correlated positively with IL-6 (r = 0.635; P = 0.014), IL-8 (r = 0.671; P = 0.001), TNF-α (r = 0.701; P = 0.001), MCP-1 (r = 0.671; P = 0.001), and MIP-1β (r = 0.614; P = 0.04)." (PMID 23690657, 2013). "The serum TNF-α levels of the patients with bacterial infections correlated positively with IL-8 (r = 0.577; P = 0.012), MCP-1 (r = 0.556; P = 0.016), and MIP-1β (r = 0.738; P < 0.001) serum levels." (PMID 23690657, 2013). "The critical indicators of the pathogenesis of bacterial infection are the copious amount of production of pro-inflammatory cytokines TNF-α and IFN-γ predominantly by macrophages and T cells." (PMID 23326499, 2013).